IRF4 (interferon regulatory factor 4)
Diseases named in the same sentence as IRF4 in open-access papers (continued):
Sharing a sentence is not in itself a finding about the gene and the disease.
tumor (203 papers, 2006 to 2026). "Our findings demonstrated that IRF4‐mediated SOX9 induction in BCL2‐overexpressing DLBCL was associated with tumour progression, suggesting the potential therapeutic implication of the IRF4‒SOX9 signalling axis in this type of DLBCL." (PMID 40356256, 2025). "IRF4 depletion in Tregs resulted in delayed tumor growth and the abundance of IRF4 + Tregs was associated with an inferior prognosis." (PMID 38918817, 2024). "Persistent antigen stimulation due to tumor or chronic viral infection can cause constitutively high expression of IRF4, which in turn induces CD8+ T cell exhaustion." (PMID 36814912, 2023). "IRF4 is implicated in B cell malignancies, acting both as tumor suppressor and as tumor oncogene in different types of precursors and mature B cell neoplasia." (PMID 36495369, 2023). "Concomitantly, IRF4-C99R upregulated myeloid-associated genes, phenocopying a central feature of cHL tumor cells." (PMID 37935654, 2023). "IRF4 expression has been associated with the presence and activity of M2 macrophages in the tumor, which are known to promote tumor development and immunosuppression." (PMID 38260202, 2023). "IL-9 mRNA levels in tumours showed a marked correlation with the Th9-associated transcription factors Irf4, Gata3, and Spi1, as well as with Socs3." (PMID 35793807, 2022). "Mainly expressed in plasma cells, IRF4 was reported to be associated with tumor stage, histological grade, and completeness of chemotherapy." (PMID 33785763, 2021). "In this study, we show that global IRF4 deficiency accelerates tumor growth, increases frequencies of tumor-infiltrating PMN-MDSC and reduces survival in a murine PDAC model." (PMID 32448983, 2020). "Here, we show that IRF4 deficiency accelerates tumor growth and reduces survival, accompanied with a dense tumor infiltration with PMN-MDSC and reduced numbers of CD8+ T cells." (PMID 32448983, 2020). "We next sought to provide evidence for a tumor suppressive action of IRF4 re-activation underlying the therapeutic benefit to a combined ERRα and DNMT drug therapy in BC." (PMID 32855526, 2020). "Among these, we have identified miR-125a-3p and miR-320c as potential tumor suppressor microRNAs as they were predicted to target MM-associated oncogenes; IRF-4, XBP-1 and BLIMP-1." (PMID 28664185, 2017). "Lower expression of IRF4 in people the allele apparently results in lower expression of all its target genes necessary for tumor growth, thus slowing its progression down." (PMID 28083618, 2016). "Given that the IRF4 gene has been recognised as one of the most common tumour markers, numerous studies have assessed the possible association between the IRF4 polymorphisms and cancer risk." (PMID 24906573, 2014). "Moreover, interference with Helios, a transcriptional partner downstream of IRF4 crucial for Treg stability, is another plausible mechanism, particularly since Helios has been linked to the maintenance of suppressive function in tumor‐infiltrating Tregs." (PMID 40820379, 2025). "This could indicate that the other significant correlations with tumor volume in the previous correlation analysis could be explained by the associations of growth rate and IRF4 mRNA levels in the regression." (PMID 39272860, 2024). "Moreover, tumour infiltration of large numbers of IRF4+ Tregs is associated with poor prognosis in patients with various types of human cancer." (PMID 36982782, 2023). "In addition, the genomic characterization of the patient-derived tumor xenograft models of Richter syndrome revealed the L116R IRF4 mutation in the mutational profile." (PMID 36495369, 2023). "One can therefore argue that the elevated levels of PMN-MDSC in the global IRF4 deficient mouse could be a secondary effect of the increased tumor size." (PMID 32448983, 2020).
tumor (continued). "A large-scale bisulfite genomic sequencing analysis revealed specific methylation perturbations fostering the discovery that reversal of promoter hypermethylation and consequently derepression of the tumor suppressor gene, IRF4, is a factor underlying the observed BC suppressive effects." (PMID 32855526, 2020). "Besides the minor effects of myeloid-specific deletion of IRF4, the accelerated tumor growth in global IRF4-deficient mice demonstrates a central role of IRF4 in shaping the TME and anti-tumor immunity." (PMID 32448983, 2020). "We also observed subclonal copy gain of KRAS in all 8 samples, as well as subclonal copy loss of both ELOVL2 and IRF4, all of which have been identified in tumours although the effect of these copy number losses in AML is unknown." (PMID 31645898, 2019). "Loss of IRF4, an event we observed in all of our resistant replicates, is reported to be associated with leukemic progression in both lymphoid and myeloid cells, which is consistent with the tumour suppression function of this protein." (PMID 31645898, 2019). "In the TME, PMN-MDSC frequency was significantly increased in Irf4−/− mice, whereas the frequency of CD8+ T cells was dramatically reduced, indicating a profound immunosuppressive TME in mice deficient for IRF4 that may account for the more rapid tumor progression in these mice." (PMID 32448983, 2020). "Our findings of the decreased IRF4 due to CAMK2D suppression are consistent with tumor and lipid phenotypes of IRF4." (PMID 39840457, 2025). "The inconsistency can be attributed to the multifaceted roles of BATF and IRF4, which can contribute to either effector or exhaustion programs depending on T cell types, tumor models, and experimental conditions." (PMID 40693464, 2025). "We showed that IRF4‐ASOs significantly reduced tumour volume and downregulated IRF4 transcription in xenograft models." (PMID 40356256, 2025). "By potentially recruiting immature B cells while impairing their maturation, IRF4 contributes to an ineffective anti-tumor immune landscape, offering a promising target for therapeutic intervention." (PMID 40607252, 2025). "Remarkably, the expression of bona fide exhaustion-related transcription factors TOX- and IRF-4 was significantly less in aCEA-28ζ-sSF6 CAR T cells relative to control CAR T cells following three rounds of repetitive stimulation with tumor cells." (PMID 40558528, 2025). "Then, since IRF4 is a key TLS-associated gene with unclear functions in ccRCC, we investigated its specific contribution to tumor progression and TLS maturation." (PMID 40607252, 2025). "Silencing IRF4 reversed the anti-tumor effects of the combination, demonstrating its central role in tumor suppression." (PMID 41008798, 2025). "IRE1α silencing increases inhibitory IRF4 phosphorylation, reducing its activity and slowing tumor growth." (PMID 41372991, 2025). "qPCR analysis of tumours from each group revealed that Pknox2, Irf4, Pou3f1, Cebpb, and Meox1 were significantly upregulated by propionate and B. fragilis." (PMID 40715695, 2025). "Complementing the single-cell perspective, our spatial transcriptomics analysis provided crucial context regarding IRF4's location within the tumor architecture." (PMID 40607252, 2025). "Consistent with prior reports in other cancers such as OSCC 51, IRF4 expression was higher in tumor tissues compared to normal tissues." (PMID 40607252, 2025). "We identified IL16 and IRF4 to be broadly downregulated in tumor-infiltrating DCs, CXCR4 to be broadly upregulated, and IL18 and IL22RA2 increases to be associated with cDC2s." (PMID 39932553, 2025). "BATF and IRF4 overexpression reduced exhaustion, promoted effector functions, and enhanced tumor-infiltrating CAR-T cells." (PMID 40693464, 2025). "In the TME, IRF4 has been shown to affect antigen presentation and the infiltration and function of immune cells, consequently promoting or suppressing tumor progression in a context-dependent manner." (PMID 40733503, 2025).
tumor (continued). "The mRNA expression of CC-chemokine ligand (CCL) 18, growth differentiation factor (GDF) 15, and interferon regulatory factor 4 correlated positively with tumor volume." (PMID 39272860, 2024). "Several studies have underscored the essential role of IRF4 in MM cell survival, with genetic knockdown of IRF4 or targeting the tumor suppressor miR-125b being fatal to MM cells." (PMID 38792604, 2024). "In MM cells, Myc, and interferon regulatory factor 4 (IRF4) form a positive autoregulatory loop, and this regulatory loop supports the survival of tumor cells." (PMID 39031503, 2024). "In contrast, another study showed that depletion of IRF4 using the DTR system compromised tumour control of by endogenous CD8+ T cells and impaired the efficacy of adoptively transferred T cells." (PMID 39399500, 2024). "The percentage of mutations in the genes was below 5% in a variety of tumours, except in DLBC where the frequency of mutations in IRF4 and IRF8 was 14% and 8%." (PMID 38130025, 2024). "The mRNA levels of the cytokines CCL5, CCL18, and GDF15, as well as the transcription factor IRF4, showed a positive correlation with the tumor volume." (PMID 39272860, 2024). "Combined in vivo and in vitro genome-wide CRISPR screens of genes related to CD8+ T cell fitness identified Roquin-IRF4 axis as a pivotal component in T cell expansion and anti-tumour immunity." (PMID 38581063, 2024). "The mRNA levels of the cytokines CCL5, CCL18, and GDF15, as well as the transcription factor IRF4, correlated weakly positively with the tumor volume." (PMID 39272860, 2024). "We identified many additional immune features, including the tumor mRNA abundance of the transcription factor, irf4, which was substantially downregulated in combination, but not monotherapy." (PMID 38670099, 2024). "IRF4 is an important transcription factor for Treg cell differentiation in TME and is associated with the formation of tumor suppressor microenvironment." (PMID 38155221, 2023). "MUM1/IRF4 was also strongly positive in tumor cells, and considered together with PAX5 positivity, indicated the nongerminal center origin of this tumor." (PMID 36992464, 2023). "IKZF1/3 control IRF4 expression and its downstream effector c-Myc are the main drivers for tumor cell growth in MM." (PMID 38344143, 2023). "By coincidence, proper reduction of IRF4 contributes to the generation of TCF1+ memory T cells that control tumor recurrence." (PMID 36814912, 2023). "To achieve this, we generated an Irf4GFP-DTR mouse strain and discovered that CD8+ tumor-infiltrating lymphocytes (TILs) expressing high levels of IRF4.GFP exhibited a more differentiated PD-1high cell phenotype." (PMID 38178902, 2023). "IRF4 downregulation augmented the CAR-triggered elimination of tumor cells with low antigen levels whereas CEA-28ζ-K control CAR T cells did not exhibit significant cytotoxicity towards GFP-labeled MIA PaCa-2 cells." (PMID 37287982, 2023). "For instance, miR-125b exhibits anti-MM and tumor-suppressor activity in vitro and in vivo by significantly downregulating interferon regulatory factor 4 (IRF4) expression." (PMID 37987364, 2023). "Through these complementary approaches, we demonstrated that IRF4+ TILs play a crucial role in tumor control." (PMID 38178902, 2023). "These proteins are key IRF4-downstream effectors that improve anti-tumor activities and enhance survival rates in MM." (PMID 37987364, 2023). "Unfortunately, IRF4 expression is remarkably suppressed during the development of MDSCs and tumor formation in the TME." (PMID 36814912, 2023). "Nevertheless, inhibiting the interaction between BATF and IRF4 will greatly weaken the tumor control ability of BATF-overexpressing CAR-T cells." (PMID 36814912, 2023). "In the field of OSCC, IRF4 were highly expressed in OSCC tumor samples compared to control samples and involved in tumor immunity-related signaling pathways." (PMID 36797470, 2023).
tumor (continued). "CCR8 is a chemokine receptor that has recently been identified as a potential specific marker for tumor-infiltrating Tregs and a core member of the interferon regulatory factor 4 (IRF4)-dependent “effector” Treg gene program." (PMID 37182149, 2023). "Collectively, growing evidence implicates IRF4 plays a central role in the differentiation and immunosuppressive activity of Treg cells in the TME, and IRF4+ Treg cells definitely inhibit anti-tumor immunity." (PMID 36814912, 2023). "For Patient 3, the engrafted tumour and the relapse biopsy both demonstrated amplification and high expression of IRF4." (PMID 37357529, 2023). "PU.1, an E-twenty-six family transcription factor, has been reported as a transcriptional factor suppressing IRF4 expression, acting as a tumor suppressor in MM." (PMID 35338347, 2023). "IRF4 is a transcription factor in inflammatory signalling and plays an essential role as a tumour promoter or suppressor depending on the cancer type or cell." (PMID 37341064, 2023). "Given its role as a key transcription factor limiting pre-B cells expansion and favoring pre-B cell differentiation, IRF4 functions as a tumor suppressor against pre-B cell transformation." (PMID 36495369, 2023). "IRF4 down-regulation via IRF4 antisense oligonucleotide (ASO) ION251 reduced tumor formation and myeloma dissemination, eradicated myeloma progenitors and improved survival and sensitivity to myeloma drugs." (PMID 36495369, 2023). "Accordingly, inhibition of IRF4 severely impaired the development and function of Treg cells at the tumor-infiltrating sites and significantly repressed tumor growth in a mouse model." (PMID 36814912, 2023). "IKZF1 functions as a tumour suppressor via transcriptional repression of oncogenes in normal hematopoietic lineages, whereas it activates IRF4 and other oncogenes in MM cells." (PMID 37581569, 2023). "Under conditions of repetitive antigen stimulation, CAR T cells with downregulated IRF4 performed superior with respect to anti-tumor effector functions as compared to conventional CAR T cells." (PMID 37287982, 2023). "A deletion exclusively in Tregs Interferon Regulatory Factor 4 (IRF4) delayed tumour growth in mice." (PMID 36982782, 2023). "Accelerated tumor growth was found upon DT treatment, which correlated with the depletion of IRF4+ TILs." (PMID 38178902, 2023). "Of note, all PU.1/IRF4 and about 50% PU.1/IRF8 double deficient mice developed pre-B ALL with reduced expression of the tumor-suppressor genes IKAROS, Blnk and Spi-B." (PMID 36495369, 2023). "In particular, an increase in intratumoral IRF4+ Treg cells with superior suppressive activity was significantly correlated with early tumor recurrence and poor disease-free survival (DFS) and overall survival (OS)." (PMID 36814912, 2023). "Together, these results indicate that IRF4 can produce and sustain a unique transcriptional program that characterizes tumor type, thus implicating its role as an oncogenic master transcription factor." (PMID 36077849, 2022). "These researches showed that it was possible to inhibit the expression of IRF4 in tumor cells and relieve the immunosuppressive effect to achieve the effect of treating DLBCL." (PMID 35983077, 2022). "Intriguingly, the physical interaction of BATF with the IRF4 transcription factor was essential for the improvement of anti-tumor responses and prevention of exhaustion in the tumor-specific CAR T cells." (PMID 35251035, 2022). "What is more, on the one hand, the high expression of IRF4 in tumor can inhibit function of effector T cells and on the other hand increases the proportion of immunosuppressive cells Treg, which promote the immune escape of cancer cells." (PMID 35983077, 2022).
tumor (continued). "IRF4 negatively regulates the immunosuppressive function of MDSCs and IRF4 in peripheral blood G-MDSCs was significantly decreased after 3 weeks of tumor bearing." (PMID 35013108, 2022). "Our research showed that it was possible to inhibit the expression of IRF4 in tumor cells and relieve the immunosuppressive effect to achieve the effect of treating DLBCL." (PMID 35983077, 2022). "The study showed that the induced deletion of Irf4 in Foxp3+ cells in MC38 tumor-bearing mice resulted in a significant delay in tumor growth." (PMID 36009853, 2022). "IRF4 ASO monotherapy can prevent the formation of a xenograft tumor model and MM cell proliferation and lead to improvement in animal survival rates." (PMID 36045700, 2021). "We analyzed TIMER database to identify the differences of IRF4 mRNA expression in various tumor samples and normal samples." (PMID 34195096, 2021). "IRF4 can promote proliferation and survival of both MM stem and tumor cells, and the high level of IRF4 is directly related to the decline of overall survival rate in patients with MM." (PMID 36045700, 2021). "The mechanism of c-Myc regulation by IRF4 in MDSCs was further investigated in the tumor microenvironment." (PMID 33708218, 2021). "Tumor-infiltrating Treg cells with increased expression of IRF4 were highly activated and preferentially expanded in lung, liver, and melanoma tumors compared with the adjacent normal tissues." (PMID 33748292, 2021). "The splenic PMN-MDSCs from tumor-bearing WT and IRF4 KO mice were sorted by flow cytometry and mixed with T lymphocytes derived from allogeneic mice in different ratios (stimulated by ConA and labeled with CFSE)." (PMID 33708218, 2021). "Three weeks later, bone marrow (BM), spleen (SP), lung, peripheral blood (PB), and tumor tissue were picked out from B16-bearing WT and IRF4 KO mice." (PMID 33708218, 2021). "We found that the expression of interferon regulatory factor 4 (IRF4) in the MDSCs of the tumor group was significantly down-regulated." (PMID 33708218, 2021). "Overtime, some functional (e.g., M-CSF and GM-CSF) and transcriptional (e.g., IRF4 and MAFB) factors in the TME induce monocyte differentiation into pro-tumoral, tumor-associated macrophages and dendritic cells, which help tumor cells avoid cytotoxic T cells." (PMID 33968780, 2021). "The results showed that the weight ratios of tumor/body and spleen/body were significantly increased in the IRF4 KO mice (P<0.05)." (PMID 33708218, 2021). "More interesting is that the elimination of PMN-MDSCs can clearly reverse tumor growth and lung tumor metastasis in IRF4 KO mice." (PMID 33708218, 2021). "Results showed that the proportion and absolute number of MDSCs in samples from the IRF4 KO mice were significantly increased in both the tumor metastasis models (P<0.05) and tumor growth models (P<0.05)." (PMID 33708218, 2021). "Consistent with the experimental results in mice, the expression of IRF4 was also positively correlated with the gene expression of c-Myc in the PMN-MDSCs from tumor patients." (PMID 33708218, 2021). "Considering IRF4 is specifically expressed in lymphocytes, we think that the value of its protumor effect in tumor cells is limited useful and its antitumor effect in lymphocytes is more important in clinical." (PMID 34195096, 2021). "The results showed that the volume of tumor in the skin of IRF4 KO was bigger than that in the WT mice on day 17, day 20, and day 23 (P<0.05)." (PMID 33708218, 2021). "IRF4 deficiency caused a significant elevation of PMN-MDSCs and enhanced the suppressive activity of PMN-MDSCs, increasing tumor growth and metastasis in mice." (PMID 33708218, 2021). "Based on our GSEA results, we further assessed the relationship between IRF4 mRNA expression and tumor immune infiltrations." (PMID 34195096, 2021). "The results demonstrated that the PMN-MDSCs derived from IRF4 KO mice possessed a greater ability to promote tumor invasion compared with those from the WT group (P < 0.01)." (PMID 33708218, 2021).